ERBB3 (erb-b2 receptor tyrosine kinase 3)
Diseases named in the same sentence as ERBB3 in open-access papers (continued):
Sharing a sentence is not in itself a finding about the gene and the disease.
tumor (continued). "In addition, gains in cyclin-dependent kinase 2 (CDK2) and erb-b2 receptor tyrosine kinase 3 (ERBB3) were found only in recurrent lesions (37.5% and 37.5%, respectively) but not in the corresponding primary tumor controls." (PMID 36135044, 2022). "Fifteen Tasmanian devils without neoplasia (twelve adults either wild caught, free range or captive enclosures and three captive juveniles encompassing CHD, CHDD and CHJD) were studied with an average serum ERBB3 of 32 pg/ml." (PMID 28591206, 2017). "When Necl-4 does not sufficiently inhibit the dimerization of ErbB3 with ErbB2, PTPN13 may complement the tumour suppressive function of Necl-4." (PMID 28900130, 2017). "Inhibition of ErbB signalling, even when targeting both EGFR and ErbB3, may not be sufficient to effectively halt PDAC tumour progression." (PMID 21792199, 2011). "Upon neuregulin stimulation, both ErbB3 and ErbB3 phosphorylation sites on PROTAC are phosphorylated, leading to recruitment, ubiquitinylation, and subsequent degradation of PI3K, and thereby reduced tumor growth by 40% in a murine model with no apparent side effects." (PMID 38213543, 2023). "However, recent gene expression profiling shows that these two models are highly similar, suggesting that the difference in the route of tumor initiation in the ApcMin/+ and AOM models likely does not contribute to molecular differences resulting in ERBB3 sensitivity." (PMID 34843459, 2021).
cancer (700 papers, 1992 to 2026). A tumor composed of atypical neoplastic, often pleomorphic cells that invade other tissues. "In particular, ErbB3 has been linked to the migratory behavior and metastasis of cancer cells and is responsible for acquired resistance to anti-EGFR therapies." (PMID 41348103, 2026). "Genomic profiling has identified ERBB2 amplification and mutations, encoding overexpressed or hyperactivated HER2, and ERBB3 (encoding HER3) alterations as drivers of human cancers." (PMID 40178042, 2025). "ERBB3 alterations were found to co-occur with ERBB2 mutations in all cancer types assessed except for NSCLC." (PMID 40178042, 2025). "ERBB3 has a somatic mutation frequency of 2.1% in pan-cancer analysis with relatively high frequencies observed e.g. in urothelial (7.3–9.8%), endometrial (8.2–12.8%), lung (1.4–8.8%), and colorectal (5.4–6.2%) cancer (cbioportal.org)." (PMID 38806620, 2024). "EGFR (epidermal growth factor receptor) and ERBB3 (also known as HER3) are receptor tyrosine kinases that have been implicated in the development of cancer." (PMID 39330508, 2024). "ERBB3, a key member of the receptor tyrosine kinase family, is implicated in the progression and development of various human cancers, affecting cellular proliferation and survival." (PMID 38276060, 2024). "The ERBB3 gene, which encodes a well-known growth factor receptor in cancer also showed significant downregulation in MTD treated cells." (PMID 37239838, 2023). "Considering its role in therapeutic resistance the ErbB3/PI3K/Akt pathway is suggested as a major cause of treatment failure in cancer therapy." (PMID 36851915, 2023). "From a functional standpoint, it has been shown that the transmembrane region of ERBB3 confers a ligand-dependent calcium influx, and loss or down-regulation of ERBB3 in cancer cells results in cellular apoptosis." (PMID 36672630, 2023). "ERBB3 encodes a member of the epidermal growth factor receptor family of receptor tyrosine kinases and plays an important role in several cancers." (PMID 36727489, 2023). "Its sensitivity analysis suggested inhibition of ligand binding to ErbB3 (also known as HER3) as a more successful approach in cancers associated with ligand-induced stimulation of ErbB-PI3K signaling mediated by combinatorial receptor activation." (PMID 36851915, 2023). "Taken together, these results suggested that Ad-mediated silencing of ErbB3 caused cancer cell death by apoptosis." (PMID 35806132, 2022). "The activation of PI3K/Akt signaling has been implicated in the ErbB3-dependent progression of various types of cancer." (PMID 35089466, 2022). "In this report, we provide the first evidence that DARPP-32 overexpression in EGFR-mutated LUAD promotes ERBB3-mediated oncogenic signaling to drive EGFR TKI therapy-refractory cancer progression." (PMID 34675407, 2022). "These cells show also the typical reduction of GFAP expression, a hallmark of cancer cells associated to the overall increase in ErbB3 synthesis, as shown from qPCR analysis performed on total RNA extracted from patient biopsies." (PMID 35255831, 2022). "We found an ERBB3 nonsense variant in a patient with monolateral infiltrating ductal BC and a positive cancer history among both paternal and maternal relatives." (PMID 34026625, 2021). "HER2 (ERBB2/neu) and HER3 (ERBB3) are receptor tyrosine kinases implicated in cancer invasion and metastasis." (PMID 33467681, 2021). "ERBB3 amplification, overexpression, and mutations contribute to the development, progression and acquired drug resistance in human cancers." (PMID 36618440, 2021).
cancer (continued). "Because of the high PI3K binding capacity, protein kinase B (AKT) signaling is strongly activated by ERBB3, which results in an oncogenic stimulus frequently implicated in many cancers and during therapeutic resistance." (PMID 34843459, 2021). "No other recurrent somatic mutations were found in the pure IDP cohort; however, single cases had known cancer hotspot mutations in ERBB3 and HRAS, and a missense mutation in SPEN." (PMID 32195332, 2020). "We used the crystal structures of the EGFR, ErbB2, ErbB3, and ErbB4 kinases that constitute this family to perform rigidity decomposition and then align the positions of the predicted cancer driver mutations with the structural mobility maps." (PMID 31245384, 2019). "Mutations and overexpression of ERB receptors (ERBB2 and ERBB3 in this network) have been strongly associated with more than 10 types of tissue-specific cancers and they can be seen at the highest level regulating most of the acyclic network." (PMID 30225028, 2018). "The current study demonstrates the functional relevance of ErbB3 nuclear localization in PCa and provides new clues for the understanding of pathways associated with cancer progression and therapy resistance." (PMID 27191720, 2016). "Among cancer-associated molecules were ERBB3 that was downregulated and ERBB4 that was upregulated in BRAFwt PTCs." (PMID 25922907, 2015). "The erbB3/PI-3 K/Akt pathway is a major cause of treatment failure in cancer therapy because of its role in therapeutic resistance." (PMID 24886126, 2014). "Recent findings on trans-autophosphorylation ERBB3 activity and oncogenic ERBB3 mutation in human cancers have marked ERBB3 as an even more potent target for cancer therapy." (PMID 24970817, 2014). "Studies on the underlying mechanisms implicate erbB3 as a major cause of treatment failure in cancer therapy, mainly through activation of the PI-3 K/Akt, MEK/MAPK, and Jak/Stat signaling pathways as well as Src kinase." (PMID 24886126, 2014). "Mechanistic studies implicate the function of erbB3 as a major cause of treatment failure in human cancers." (PMID 24168763, 2013). "ERBB3 encodes a transmembrane tyrosine kinase receptor, which has previously been associated with cancer in a large number of studies (>500 publications)." (PMID 23835063, 2013). "Cancer-associated fibroblasts-derived NRG-1 promote PDAC tumourigenesis via ErbB3-AKT signalling and overcomes single-agent EGFR inhibition." (PMID 21792199, 2011). "The purpose of our study was to analyse the role of cancer-associated stroma in PDAC progression while delineating the effects of targeted ErbB3 inhibition in combination with anti-EGFR therapy." (PMID 21792199, 2011). "The epidermal growth factor receptor (EGFR) family of receptor tyrosine kinases, which consists of EGFR, ErbB2, ErbB3, and ErbB4, is important in many normal developmental processes and is often over-expressed or mutated in human cancer." (PMID 19019207, 2008). "ERBB3 mutational hotspots likewise varied across cancer types." (PMID 40178042, 2025). "ERBB3 mutational profiles were less variable across cancer types." (PMID 40178042, 2025). "Additionally, lncRNA‐SNHG15 has been identified as a regulator of downstream genes such as MYC, NRAS, BAG3, and ERBB3, all of which are closely associated with cancer progression." (PMID 40620190, 2025). "Previous studies have identified few transforming ERBB3 mutations while the great majority of the hundreds of different somatic ERBB3 variants observed in different cancer types remain of unknown significance." (PMID 38806620, 2024).
cancer (continued). "Given that across all cancers, somatic ERBB3 mutations occur at a frequency of 2.1%, these findings support a rationale for treating cancers with these alterations with kinase inhibitors and/or therapeutic antibodies targeting ErbB2/ErbB3." (PMID 39120280, 2024). "While hundreds of different somatic ERBB3 mutations have been reported in clinical samples representing a number of different cancer types, the functional significance of the variants is mostly unknown." (PMID 38806620, 2024). "ERBB3 mutations can occur in various cancer entities, but are overall rare events." (PMID 38664720, 2024). "Additionally, ERBB2 and ERBB3 gain-of-function mutations have been shown to contribute to the occurrence and development of a variety of cancers." (PMID 31752936, 2019). "ERBB3 is also a protein known to be overexpressed and mutated in cancer cells." (PMID 30421568, 2019). "Gain-of-function pathogenic variants of the Erb-B2 receptor tyrosine kinase 3 (ERBB3) gene contribute to the occurrence and development of a variety of human carcinomas through activation of phosphatidylinositol 3-kinase (PI3K)/AKT and extracellular signal-regulated kinase (ERK) signaling." (PMID 31752936, 2019). "High ErbB3 levels have been linked to resistance in cancer therapies that target ErbB1 or ErbB2." (PMID 29361123, 2018). "Cancer-related ERBB3 mutations are relatively uncommon, except for colon and gastric carcinomas." (PMID 30367623, 2018). "Thus, both p-ErbB2 and p-ErbB3 are—despite their mutual interdependence—individually contributing to the survival of treated cancer cells by causing reactivation of AKT." (PMID 27255951, 2016). "Since PI-3 K/Akt signaling is the most important survival pathway in cell proliferation and its activation often leads to multidrug resistance in human cancers, it is understandable that one of the major biologic consequences of erbB3 activation is to cause treatment failure in cancer therapy." (PMID 24886126, 2014). "The physical association of ErbB1 with c-Met, ErbB2, or ErbB3 expands the network of signaling pathways that are activated in cancer cells and illustrates why a single tyrosine kinase inhibitor may not be sufficient to eradicate disease." (PMID 23866081, 2013). "By combining EGFR, ERBB2, and ERBB3 protein expression in a decision tree model, we identified an association with biochemical recurrence (log rank = 25.295, p < 0.001), development of bone metastases (log rank = 23.228, p < 0.001), and cancer-specific mortality (log rank = 24.586, p < 0.001)." (PMID 33918389, 2021). "Chen Y., Lu A., Hu Z., Li J., Lu J. ERBB3 targeting: A promising approachto overcoming cancer therapeutic resistance." (PMID 41541554, 2025). "METTL13 knockdown inhibited B-ALL driver gene NRAS, and ERBB3, which is frequently overexpressed in cancer." (PMID 41282185, 2025). "Compared to adjacent normal mammary glands, TSG101-overexpressing carcinomas show higher levels of ERBB3, HRAS, and active AKT (left)." (PMID 40624726, 2025). "The receptor tyrosine kinase (RTK) ERBB3 is another pseudokinase frequently attributed a role in cancer." (PMID 38806620, 2024). "ERBB3 overexpression occurs in several cancers and has a central role in the development of drug-resistance to several tyrosine kinase inhibitors including ALK-TKI." (PMID 39695132, 2024). "The discovery of gene fusions involving Neuregulin-1 (NRG1) within solid tumors has important therapeutic implications, as they are being actively explored as targets for emerging ERBB/ERBB2/ERBB3-directed anti-cancer agents." (PMID 39575425, 2024). "HER3 (ErbB3), a member of the human epidermal growth factor receptor family, is frequently overexpressed in various cancers." (PMID 38632563, 2024). "Increased NRG1 expression can activate downstream signaling pathways, such as the ERBB2/ERBB3 pathway, which promotes cancer cell proliferation, migration, and survival." (PMID 38957319, 2024).
cancer (continued). "Taken together, several drugs that target ERBB2/HER2 and/or ERBB3/HER3, including small molecule inhibitors and antibodies, have shown evidence of pan-cancer activity in NRG1 fusion bearing malignancies." (PMID 38369520, 2024). "The role of ERBB3 in cancer biology is complex, as it is involved in cell proliferation, differentiation, and survival." (PMID 38276060, 2024). "Delivering therapeutics to ErbB3-expressing cancer cells with anti-ErbB3 ADCs is a promising area for clinical trials." (PMID 39020378, 2024). "This approach adds granularity to our understanding of ERBB3’s role in cancer, enabling us to piece together a more comprehensive picture of its multifaceted involvement." (PMID 38276060, 2024). "Given the importance of ERBB3 to be frequently upregulated in several cancers and its implication in drug-resistance, a huge effort has been put for the development of anti-ERBB3 therapies." (PMID 39695132, 2024). "More indirect targeting of the potently transforming heterodimeric complex of ERBB3 with ERBB2 (with anti-ERBB2 drugs or compounds such as bispecific ERBB3/ERBB2 antibodies) provides another route for activity against ERBB3-driven cancer." (PMID 38806620, 2024). "Among the top three candidates for both gains and losses, CDKN2C gain, KIT loss, and GNAS loss were unique to GC cell lines, while ERBB3 gain, FBXW gain, and hypoxia-inducible factor 1a loss were also observed in other cancer types." (PMID 39461475, 2024). "Whereas sapitinib has an enhanced pharmacologic profile due in part to equipotent inhibition of EGFR, erbB2, and erbB3, showing potent antitumor activity in preclinical cancer models." (PMID 36982163, 2023). "Some of the most well-characterized RTKs implicated in cancer include the “HER family”, i.e., epidermal growth factor receptor (EGFR), ErbB2 (neu, HER2), ErbB3 (HER3) and ErbB4 (HER4), as well as VEGF/VEGFR, which is discussed in the following paragraphs." (PMID 38136430, 2023). "LncRNA-SNHG15 regulated the expression of downstream genes including MYC, NRAS, BAG3, and ERBB3, which are closely related to cancer progression." (PMID 35617032, 2022). "In the present study, we aimed to develop an Ad vector system expressing ErbB3-specific shRNA (shErbB3) for cancer therapy." (PMID 35806132, 2022). "The presence of ErbB3 in the nucleolus has been described in several cancer cell lines but its function in this compartment remains unexplored at moment." (PMID 35255831, 2022). "The ERBB3 model also plays a role in improving the predictions for CDK4, which is known to participate in inactivating RB gene in many cancers through loss of proliferation control." (PMID 35933367, 2022). "The induction of ErbB3 expression or signaling is an important factor in drug resistance in several cancer models." (PMID 35089466, 2022). "The ErbB oncogenic receptor tyrosine kinase family proteins (ErbB1, ErbB2, ErbB3, and ErbB4) have been shown to contribute significantly to pro-proliferation, migration, invasion, and drug resistance characteristics of diverse cancer cell types." (PMID 35806132, 2022). "HER3 gene (ERBB3) amplification and overexpression are associated with resistance to a variety of cancer drugs, including chemotherapy, hormone therapy and trastuzumab." (PMID 35158800, 2022). "The overexpression of both Erbb2 and Erbb3 genes indicates an expression pattern that is common in both chronic wounds and cancer." (PMID 36009225, 2022). "Previous studies have revealed that neuregulin-dependent ErbB3 and ErbB4 signaling in cancer cells contributed to VEGF-mediated angiogenesis and anti-apoptosis." (PMID 35053480, 2022). "The principal functional effect arising from the targeted inhibition of ErbB3 signaling is reduced growth and survival of cancer cells." (PMID 34572289, 2021). "Two antibodies, BCD090-P1 and BCD090-M2, noncompetitively interact with distinct epitopes on the receptor with nanomolar affinity and inhibit ErbB3-driven proliferation in cancer cells." (PMID 34572289, 2021).